LRRK2 (leucine rich repeat kinase 2)
Diseases named in the same sentence as LRRK2 in open-access papers (continued):
Sharing a sentence is not in itself a finding about the gene and the disease.
infection (continued). "Although this study was performed in the context of a specific infection, it highlights the potential of modulating LRRK2 kinase activity as a therapeutic in PD patients with monogenic LRRK2 mutation." (PMID 33291304, 2020). "In this study, we show that phagosome and endolysosome membrane damage via membranolytic agents or infection with Mycobacterium tuberculosis, Listeria monocytogenes or Candida albicans triggers LRRK2 activation." (PMID 32643832, 2020). "We detected a significant time‐dependent increase in Rab8A pT72 after infection with the pathogens confirming that infection triggers LRRK2 activation (Fig EV1A–C)." (PMID 32643832, 2020). "To prove the influence of LRRK2 dysfunction by infection, we need to examine the damage of CNS in pathogen-infected WT and LRRK2 KO mice." (PMID 32164260, 2020). "These high basal levels of type I IFN appear to completely reprogram Lrrk2 KO macrophages, rendering them refractory to a number of distinct innate immune stimuli, including infection with Mtb." (PMID 32057291, 2020). "We measured a significant defect in ISG expression 8 hr post-infection in Lrrk2 KO BMDMs and Lrrk2 KO RAW 264.7 macrophages compared to control cells." (PMID 32057291, 2020). "In light of the potential importance of LRRK2 activity in immune cell function, safety profiling should also consider to what extent will patients receiving LRRK2 inhibitors be affected by infection." (PMID 33066808, 2020). "We observed significantly more inflammatory granulomatous nodules in the lungs, specifically in the perivascular region, indicating that more macrophages had infiltrated infected lungs of Lrrk2 KO mice at Day 21 post-infection." (PMID 32057291, 2020). "We observed a significant increase in CFUs recovered at 5 days (120 hr) following infection, suggesting that while Lrrk2 KO macrophages can control Mtb replication early after infection, they are more permissive once the bacteria have established a niche." (PMID 32057291, 2020). "Infection of mouse bone-marrow derived dendritic cells with Aspergillus fumigatus also resulted in the downregulation of LRRK2 protein and increased NFAT transcriptional activity." (PMID 32210756, 2020). "It will be interesting for future studies to identify in more detail the role of (mutant) LRRK2 during peripheral infections in terms of pathogen-specific mechanisms and the involvement of specific immune cells." (PMID 32410948, 2020). "We therefore used a subclinical infection model to test for inflammatory phenotypes in Lrrk2−/− mice." (PMID 32111741, 2020). "Functional analysis in vivo in a subclinical infection model also indicated that Lrrk2 subtly modifies the inflammatory response." (PMID 32111741, 2020). "RNA-seq analysis was performed on total RNA collected from uninfected and infected cells 4 hr post-infection (Lrrk2 KO n = 4, Lrrk2 HET n = 3)." (PMID 32057291, 2020). "(A) RT-qPCR of Isg15 expression after 4 and 8 hr of infection with M. leprae (MOI = 50) in Lrrk2 KO BMDMs and HET controls." (PMID 32057291, 2020). "Our findings further support the potential roles of LRRK2 in host response to infection and neurodegeneration." (PMID 31217489, 2019). "Together, these studies imply an important but complex role for LRRK2 in controlling intracellular M. tuberculosis replication as well as in regulating systemic immune responses and inflammation during infection." (PMID 31192157, 2019). "Emerging data suggest that LRRK2 plays critical roles in immune modulation of macrophages, which is supported by the investigations on the resistance of LRRK2 to intracellular pathogen infection, including Listeria monocytogenes and Mycobacterial tuberculosis." (PMID 30670047, 2019). "At day 7 after infection with Mtb H37Rv, LRRK2 KO mice showed a significant reduction of CFUs in the lung." (PMID 29789389, 2018). "Dissemination to the spleen at day 14 after infection with Mtb H37Rv was also significantly reduced in LRRK2 KO mice when compared to WT mice." (PMID 29789389, 2018).
infection (continued). "After infection with Mtb, we observed that in LRRK2 KO mice, the transcriptional levels of type II IFN (IFN‐γ) were significantly higher and levels of type I IFN (IFN‐α) almost absent." (PMID 29789389, 2018). "A role of ROC domains in immune response mechanisms is gaining attention among human ROCO proteins; for example, MASL1 and LRRK2 have been shown to be upregulated upon pathogen infection." (PMID 24981771, 2014). "Subtle, albeit significant, changes were identified between LRRK2 knockout and wild type animals following infection with RAIV and Streptococcus pneumoniae." (PMID 23799078, 2013). "LRRK2 is a large multidomain protein that encompasses, among other domains, a kinase and a GTPase domain and serves as a pivotal regulator of vesicular trafficking, infection, immunity, and inflammation." (PMID 40867920, 2025). "Also, LRRK2 influences the release of the anti-inflammatory cytokine IL-10 in mouse macrophages following infection with Mycobacterium tuberculosis." (PMID 40867920, 2025). "However, following infection, Th17 cells demonstrated a trend towards increase in Lrrk2 G2019S-infected mice compared to WT infected." (PMID 40883285, 2025). "While this viral model has allowed us to investigate a role for these proteins in an acute, innate immunity driven infection course, assessments of Lrrk2- and α-synuclein-based anti-viral properties in adult mice are ongoing and will allow us to investigate their role in a mature immune system." (PMID 40471880, 2025). "However, when the infection reached the brain in the case of reovirus T3D, despite lower titres, Lrrk2 p.G2019S knock-in mice had worse health outcomes indicated by increased mortality, which was associated with a significant female sex bias." (PMID 40471880, 2025). "LRRK2 modulates apoptotic activity of macrophages following infection with BCG." (PMID 36972292, 2023). "Furthermore, damage of lysosomes following infection or treatment with agents such as l-leucyl-l-leucine methyl ester (LLOMe) induces recruitment of LRRK2 to lysosomal membranes." (PMID 38091401, 2023). "Moreover, the simulated chromatin structure based on single-cell Hi-C data revealed that rs1873613 and LRRK2 tended to be adjacent in space upon infection." (PMID 36195603, 2022). "Furthermore, this SNP is located right in the anchor of an LRRK2 chromatin loop that was significantly strengthened after infection." (PMID 36195603, 2022). "The ability of LRRK2 to induce an immune reaction after infections may at least in part also explain the mitochondrial phenotypes observed in cellular models of LRRK2-PD." (PMID 38835904, 2022). "In this mini review, the relationship between common bacterial (H. pylori, M. tuberculosis, P. gingivalis, C. difficile and C. pneumoniae) infection with PD and their possible action mechanisms, such as neuroinflammation factors, LRRK2 pathway and toxic protein aggregations, were revealed." (PMID 35967873, 2022). "Although the precise function of LRRK2 remains unknown, it is becoming increasingly clear that LRRK2 has a function in immunity to infection and inflammation." (PMID 32643832, 2020). "Besides IBD, LRRK2 has also been studied in the context of peripheral infections, especially infections affecting the gastrointestinal tract." (PMID 32410948, 2020). "Given the evidence for the role of LRRK2 in gastrointestinal inflammation, infection, peripheral immune responses and PD, LRRK2 may be situated in the center of this model." (PMID 32508566, 2020). "To investigate whether LRRK2 can mediate infection with intracellular pathogens, we co-cultured BMDCs with L. (L.) major for 3 days in vitro, then measured the levels of inflammatory cytokines secreted into the culture supernatants using ELISA." (PMID 32164260, 2020). "Similarly, LRRK2 appeared crucial for the antibacterial activity of macrophages during infection with Salmonella typhimurium in vitro, which was confirmed in vivo using mice lacking LRRK2." (PMID 32410948, 2020).
infection (continued). "LRRK2 dysfunction and the initiation of inflammation due to infection might be influenced by the survival of neural cells and CNS milieu." (PMID 32164260, 2020). "For instance, complete genetic inactivation of LRRK2 in vivo shows that the attenuation of a central infection may be at the expense of the efficiency of the peripheral immune system against a systemic infection." (PMID 33066808, 2020). "In LRRK2, DJ-1, and PSEN1, for example, promoter-associated antisense lncRNAs are more expressed in blood libraries than in the brain, and within blood cells, their expression is strongly activated upon infection." (PMID 30610612, 2019). "In future work, it would also be exciting to explore the biological role that the LRRK2 pathway plays in neutrophils and whether it is involved in controlling migration to the sites of the infection and/or phagocytosis and destruction of pathogens." (PMID 29127255, 2018). "In this report by Liu and colleagues, they showed that the activation of inflammasomes containing NLR family CARD domain-containing protein 4 (NLRC4) in response to the infection of pathogens was insufficient in Lrrk2 KO macrophages, leading to the reduced production of IL-1β." (PMID 32714591, 2018). "We hypothesise that LRRK2 could be one of the molecules predicted to act at very early stages of the infection." (PMID 29789389, 2018). "They found that in Paneth cells in the mouse intestine, LRRK2 localized to the membrane of dense core vesicles (DCVs), which store bactericidal substances, including lysozymes, and secrete them into the intestinal lumen upon infection." (PMID 32714591, 2018). "To further understand how LRRK2 G2019S activity may alter immunocyte proportions in the lamina propria under infectious conditions, we completed a proportional analysis of Lrrk2 G2019S against WT infection." (PMID 40883285, 2025). "Similarly in macrophages, pathogen infection induces lysosomal damage and was shown to result in relocalization of LRRK2 to the damaged lysosome where it phosphorylated Rab8A, and this recruited the ESCRT-III component CHMP4B that orchestrates the repair of lysosome damage." (PMID 38091401, 2023). "Moreover, when mice lacking Lrrk2 were infected with Mycobacterium tuberculosis, which causes tuberculosis, their lungs exhibited exacerbated local inflammation caused by the infection." (PMID 32293561, 2020). "Additionally, epidemiological studies on whether previous infections play a role in the development of PD in LRRK2 carriers compared to healthy LRRK2 carriers, will substantiate the ‘multiple hit’ hypothesis in PD." (PMID 33291304, 2020). "Interestingly, infection of IFNAR KO mice with Mtb shows a similar phenotype to the LRRK2 KO mice." (PMID 29789389, 2018). "Additional IBD risk gene, Nod2 or leucine-rich repeat kinase 2 (LRRK2) absence disturbs the lysozyme packaging and secretion of Paneth cells, thus leading to the failure in controlling pathogen invasion, which was shown by infection with Listeria monocytogenes." (PMID 28119697, 2016). "For example, LRRK2 and MASL1 were shown to be upregulated on pathogen infection, though the molecular mechanisms to modulate inflammatory response are still unclear." (PMID 39246816, 2024). "(C) Heatmap depicting significant gene expression differences (Log2 fold-change) between Lrrk2 KO and HET BMDMs during infection with Mtb." (PMID 32057291, 2020). "(D) As in (B) but for pathways enriched for differentially expressed genes in Mtb-infected Lrrk2 KO and HET BMDMs, 4 hr post-infection." (PMID 32057291, 2020). "However, following infection with BCG, apoptosis was significantly increased in LRRK2 KO cells compared to LRRK2 WT cells." (PMID 36972292, 2023). "Collectively, these results demonstrate that LRRK2’s role in maintaining mitochondrial homeostasis is critical for proper induction of type I IFN gene expression in macrophages and for downstream inflammatory responses during in vivo infection." (PMID 32057291, 2020).
infection (continued). "We observed almost absent levels of the type I IFN‐α in LRRK2 KO lungs when compared to WT lungs from Mtb‐infected mice at day 56 of infection." (PMID 29789389, 2018). "Although no side effects have been reported upon inhibition of LRRK2 in the brain, decreased systemic LRRK2 activity may induce a more permissive immune system, resulting in an inadequately controlled infection, dependent on the pathogen." (PMID 32410948, 2020). "While Mtb-infected Lrrk2 KO mice did not exhibit significant differences in bacterial burdens compared to controls, we did observe exacerbated pathology and lower expression of ISGs in the lungs at early infection timepoints." (PMID 32057291, 2020). "Thus, immunological alterations in the LRRK2 knockout rat are described in this study, but any negative impact of these alterations on host resistance to infection appears to be subtle." (PMID 23799078, 2013). "Given the evidence discussed implicating LRRK2 in the regulation of immune responses to pathogens, it is curious to speculate if epidemiological research would demonstrate increased rates of previous infections in LRRK2-PD patients relative to non-manifesting LRRK2 carriers." (PMID 32508566, 2020). "Indeed, LRRK2 activation triggered by Rab29 could occur in a specific cell type or tissue, or following a physiological stimulus, stress or infection that we have not investigated." (PMID 33135724, 2020).
tumor (27 papers, 2010 to 2026). "LRRK2 knockout in this model significantly increased tumor initiation and size, demonstrating that loss of LRRK2, a key Parkinson’s gene, promotes lung tumorigenesis." (PMID 33483550, 2021). "A number of somatic mutations in two other genes unequivocally linked to PD, namely PINK1 and LRRK2, both of which encode protein kinases, were identified in tissue samples from patients with various tumours." (PMID 21203498, 2010). "In summary, marked LRRK2 reduction was associated with tumors predicted to have altered distal lung architecture, dysfunctional surfactant metabolism, hyperproliferation and potentially altered innate tumor immunity—in patients who continued to smoke and ultimately suffered worse survival." (PMID 33483550, 2021). "This work introducing DNK72 as a novel LRRK2 inhibitor demonstrated that LRRK2 inhibition with DNK72 effectively reduced tumor growth and increased survival time." (PMID 40629324, 2025). "To elucidate the molecular mechanisms underlying the impact of LRRK2 G2019S on CAC development, we examined colon tumor tissues from AOM/DSS-treated LRRK2 KI and WT mice to assess the activation of various pro-tumor effectors." (PMID 38607004, 2024). "Consistently, NUF2, KIF4A, KIF18B, DLGAP5, and NEK2 were highly overexpressed, whereas LRRK2 was significantly downregulated in the tumor tissues of all datasets." (PMID 36499051, 2022). "These candidates included five upregulated genes—NUF2, KIF4A, KIF18B, NEK2, and DLGAP5—and one downregulated gene—LRRK2—in the tumor tissues of TCGA databases." (PMID 36499051, 2022). "Analyses from the TCGA RNA-seq data revealed LRRK2 to be significantly overexpressed in ccRCC as compared to that of non-tumor controls (p < 0.001)." (PMID 34217264, 2021). "Based on the intensity and density of IHC staining, the LRRK2 IHC score of tumor tissue is significantly higher than that of the controls." (PMID 34217264, 2021). "The results suggest that the upregulation of LRRK2 expression is related to lower tumor grade, stage, and TMN, and LRRK2 overexpression is more frequently seen in women." (PMID 34217264, 2021). "Analysis of the TCGA datasets has shown that high expression of LRRK2 is related to the gender of the patients, tumor grade, stage, metastatic status, and prognosis of ccRCC patients." (PMID 34217264, 2021). "Our data showed that knockdown of LRRK2 expression attenuats the proliferative ability of ccRCC tumor cell lines, indicating that LRRK2 has a critical role in ccRCC tumor cell growth and proliferation, but the specific mechanisms needs further investigation." (PMID 34217264, 2021). "The results showed that LRRK2 expression had significant correlations with tumor purity (r = −0.172, P = 1.28E-04) and significant correlations with various immune cells infiltration levels." (PMID 32196072, 2020). "Both the mean excised tumor volume and weight decreased more than 50% following LRRK2-IN-1 treatment for 4 weeks." (PMID 24885928, 2014). "Bioinformatics prediction and literature evidence suggest the tumor suppressive functions of LINC01133 may occur through sponging miR-205-5p to derepress the miR-205-5p targets LRRK2 and AR." (PMID 39744510, 2025). "In addition, we observed increased CD45+ leukocyte infiltration in the tumor tissue in the LRRK2 KI mice." (PMID 38607004, 2024). "The immunoblot assay suggested an increased level of COX-2 in the tumor tissues from LRRK2 KI mice." (PMID 38607004, 2024). "Furthermore, LRRK2 G2019S enhances intestinal epithelial cell proliferation and inflammation within the tumor microenvironment." (PMID 38607004, 2024). "Similarly, the average tumor load, calculated by summing the diameters of all tumors in each mouse, was significantly higher in LRRK2 KI mice compared to WT mice." (PMID 38607004, 2024).